BDNF (brain derived neurotrophic factor)
Diseases named in the same sentence as BDNF in open-access papers (continued):
Sharing a sentence is not in itself a finding about the gene and the disease.
depression (continued). "Decreased levels of the BDNF and TrkB were found in postmortem brain samples from patients with depression." (PMID 38337722, 2024). "Clinical studies have demonstrated that C-reactive protein and TNF-α are positively correlated with self-rating depression scale scores, while BDNF levels are negatively correlated with these scores in women with perimenopausal syndrome." (PMID 38255289, 2024). "On the other hand, it exacerbates mental health issues, including depression and anxiety, possibly through mechanisms involving reduced neuroplasticity and decreased levels of BDNF." (PMID 40226670, 2024). "By understanding how uPA modulates these behavioral constructs, particularly through its interactions with BDNF, we can better appreciate its potential therapeutic role in disorders characterized by chronic stress, anxiety, and depression." (PMID 39766310, 2024). "This approach successfully mitigated depression-like behaviors, illustrating BDNF’s therapeutic potential for PPD." (PMID 39588356, 2024). "There are also several lines of evidence that link BDNF to the hippocampal atrophy seen in depression, and to the efficacy of antidepressants (see for review:)." (PMID 39194496, 2024). "For instance, mice exposed to acute exogenous SCFA (sodium butyrate) are observed to have altered production of brain-derived neurotrophic factor (BDNF), which is a neuronal factor that has been associated with depression." (PMID 39155987, 2024). "This complex interplay among neuropsychological behaviors, BDNF expression, and the HPA axis was also implicated in perimenopause-associated depression, in relation to inflammatory factors." (PMID 38255289, 2024). "Pro-BDNF levels at M2 were also higher in the subsample without DE at M2, which is unexpected, as previous studies have shown that pro-BDNF levels are higher in patients suffering from depressive episodes than in controls." (PMID 39430530, 2024). "such as bipolar disorder and major depressive disorder, and alterations in BDNF levels, the imbalance between pro-BDNF and m-BDNF, and defects in the BDNF signaling pathway have been observed." (PMID 38203806, 2024). "BDNF concentration decreases in individuals with major depressive disorder and increases after antidepressant drug treatment." (PMID 39443283, 2024). "The methylation level in the BDNF gene exon IV promoter was significantly lower in the studied group compared with the control and correlated negatively with the severity of depression." (PMID 38542252, 2024). "Of the monitored tryptophan metabolites, only 5-hydroxyindolacetic acid was positively correlated with the severity of depression, total cholesterol, and negatively with brain-derived neurotrophic factor and glutathione peroxidase." (PMID 38414497, 2024). "Using AKR-, BALB/c-, and C57BL/6J-strain male mice, we examined depression-like behaviors, social reward responses, and BDNF expression." (PMID 38338875, 2024). "For example, microglial activation through the ERK pathway not only facilitates BDNF production but also modulates inflammatory cytokines and neuroimmune signaling, processes that are often dysregulated in depression." (PMID 39684808, 2024). "Overall, dysregulation of brain RAS triggers the development and progression of depression through reduction of brain 5HT and expression of BDNF and induction of mitochondrial dysfunction, oxidative stress, and neuroinflammation." (PMID 37953501, 2024). "Different studies highlighted the fact that the BDNF serum level is highly reduced in PD and correlates with cognitive dysfunction and the development of depression." (PMID 39654365, 2024). "Reduced BDNF production and signaling have been observed in postmortem brain tissue of patients with depression." (PMID 39484160, 2024). "This intervention modulated the BDNF/TrkB/AKT signaling pathway, central to neural plasticity and implicated in depression’s pathogenesis." (PMID 41221079, 2024).
depression (continued). "Their review synthesized existing literature to elucidate how BDNF affects depression-related biomarkers, including gene expression, neuroplasticity, and overall brain function." (PMID 39935805, 2024). "This upregulation enhances the production of BDNF, alleviating depression-like behavior and neuroinflammation." (PMID 38173021, 2024). "Medial prefrontal cortex (mPFC) neuronal activity and BDNF signaling play key role in resisting depression." (PMID 39619203, 2024). "Gene expression of BDNF alteration is contributed to many disorder and diseases such as epilepsy, depression, Parkinson and Alzheimer." (PMID 38528644, 2024). "Moderate intensity possesses a protective effect in reducing depression by impacting SNP rs6265 for BDNF secretion, while high-intensity exercise improves locomotor learning by influencing SNP rs6265." (PMID 39194500, 2024). "It is important to note that uPA mRNA and BDNF protein levels were also isolated from the dorsal striatum (DS), quantified, and analyzed for potential Spearman correlations with anxiety- and depression-like behavioral parameters." (PMID 39766310, 2024). "Given the critical role of BDNF in the effects of exercise on cognitive function, anxiety, and depression-like behaviours via mediating neurogenesis and synaptic plasticity, BDNF has the potential to be a promising molecular target of exercise mimetics." (PMID 39049102, 2024). "Along these lines, though somewhat controversial, it is noteworthy to mention that BDNF in the ventral tegmental area-nucleus accumbens (VTA-NAc) pathway is involved in the development of depression-like behavior." (PMID 38539677, 2024). "Physical exercise improves depressive symptoms by increasing the circulating BDNF level in patients with depression." (PMID 39654365, 2024). "A previous study reported that the plasma concentration of SIRT1 was positively correlated with BDNF levels in patients with depression." (PMID 38559694, 2024). "The remarkable ability of RVG-BDNF-Exos to alleviate depression-like symptoms in mice, induced by intraperitoneal LPS injection, is a testament to the therapeutic potential of BDNF in mood regulation and neurogenesis." (PMID 41221079, 2024). "It is important to note that, among the existing meta-analyses examining the relationship between exercise and BDNF levels in patients with depression, only four large-scale studies have been reported to date." (PMID 40226670, 2024). "Human post-mortem studies have revealed a decrease in BDNF in the hippocampus of patients suffering from depression." (PMID 39457754, 2024). "Serum levels of brain-derived neurotrophic factor (BDNF) are influenced by factors such as age, physical activity, and neuropsychiatric disorders, including dementia, depression, anxiety, schizophrenia, and bipolar disorder." (PMID 39935805, 2024). "Nevertheless, disruption or dysregulation of BDNF/TrkB signaling impairs learning and memory and induces depression." (PMID 39574138, 2024). "Brain-derived neurotrophic factor (BDNF), a protein with significance in depression, drug addiction, and aging, also plays an important role in stress resistance and chronic resilience." (PMID 38732113, 2024). "The results revealed that the gut microbiota from Sig-1R KO mice induced depression-like behavior by modulating the cAMP/CREB/BDNF signaling pathway, and furnished supportive evidence for subsequent investigations into the brain-gut axis." (PMID 38983862, 2024). "Chronic stress, a well-established precipitating factor for depression, can lead to a decrease in BDNF support." (PMID 39478958, 2024). "In fact, pro-BDNF induces neuronal apoptosis and long-term synaptic depression, whereas BDNF promotes neuronal survival, facilitates neurogenesis and dendritic growth, and is crucial for long-term potentiation in the hippocampus." (PMID 39766310, 2024). "Accumulating evidence showed that brain BDNF level is reduced in experimental animals and patients with depression." (PMID 38178196, 2024).
depression (continued). "Changes in BDNF expression in depression have also been identified on the molecular level in the epigenetic modifications of the BDNF gene." (PMID 38542252, 2024). "The functional mechanism of ZZCD via the Six3os1/BDNF axis unveiled in the current study provides novel therapeutic hints for depression prevention and treatment." (PMID 38818577, 2024). "Only a handful have explored the longitudinal relationships between cognitive function and both inflammatory factors and BDNF in first-episode major depressive disorder." (PMID 39911552, 2024). "Research has proved that hippocampal CREB phosphorylation (p-CREB) promoted the expression of BDNF and alleviated depression-like behaviors in lipopolysaccharide-treated mice." (PMID 38372284, 2024). "Following the results of adult studies, we assumed a decreased BDNF serum level, increased proBDNF serum level, and increased BDNF exon IV promoter methylation profile to characterize adolescent depression." (PMID 38542252, 2024). "This study demonstrates that a range of exercise interventions can significantly elevate BDNF levels in patients with depression, with AERE, RE, and yoga showing the most substantial effects, followed by Qigong, mindfulness, and CAE." (PMID 40226670, 2024). "Nicotinamide riboside altered the gut microbiota composition in an alcohol-induced depression rat model, leading to elevated BDNF levels in the hippocampus and decreased production of inflammation-related cytokines." (PMID 39459643, 2024). "By inhibiting the transcription factor CREB, BAs can suppress the transcription of BDNF, suggesting a potential influence of BAs on depression." (PMID 38357350, 2024). "Two studies have shown that chronic administration of 7,8-dihydroxyflavone improves depression-like behaviors in rats by acting as an agonist on the TrkB receptor, which subsequently increases hippocampal expression of BDNF." (PMID 39478958, 2024). "Synaptic plasticity is impaired in depression by the dysfunction of or reduction in BDNF levels, reduction in excitatory neurons, and glutamate." (PMID 39519391, 2024). "Previous studies have shown the deficits of postsynaptic proteins PSD95 and synaptic plasticity-related protein BDNF in synaptic plasticity, cognitive function and depression." (PMID 39588497, 2024). "Changes in BDNF activity and levels in the brain are closely related to the development of depression." (PMID 38628641, 2024). "The neurotrophic theory of depression suggests that reduced levels of brain-derived neurotrophic factor (BDNF) in individuals suffering from depression are crucial in the development of this mental health condition." (PMID 39684342, 2024). "In the mPFC in rats with ICV-STZ-induced depression-like behavior, we found a decrease in BDNF levels, accompanied by a reduction of mushroom-type dendritic spines." (PMID 38720779, 2024). "In a study involving CUMS rats subjected to 28 days of CSS oral administration, it was observed that compared to the depression model group, the expression of BDNF in the prefrontal cortex of rats significantly increased." (PMID 38628641, 2024). "Individuals with depression often exhibit reduced levels of BDNF, which tend to rise after effective antidepressant therapy." (PMID 39624510, 2024). "A substantial body of evidence suggests that individuals with depression exhibit reduced levels of BDNF, a finding consistently reported in both serum and brain tissue samples." (PMID 40226670, 2024). "Around the same time, another study was published on intranasal therapy for depression using brain-derived neurotrophic factor (BDNF)." (PMID 39062095, 2024). "One study showed that sodium butyrate exerts antidepressant-like effects, with an increase in TET1 leading to elevated 5hmC levels in the BDNF gene in the prefrontal cortex in a rat model of depression." (PMID 38410811, 2024).
depression (continued). "For instance, increased expression of serotonin and glutamate receptor genes has been observed in females, whereas males show a reduction in BDNF-dependent genes and BDNF receptor TrkB expression post-depression." (PMID 38377025, 2024). "For instance, N-acetylcysteine ameliorates chemotherapy-induced impaired anxiety and depression-like behaviors by regulating BDNF release." (PMID 39703344, 2024). "A study has suggested that alteration of BDNF production is also involved in the neuropathic processes related to obesity, such as depression." (PMID 40255947, 2024). "In conclusion, the present study suggests a potential link between elevated neopterin levels, decreased IL-4, and BDNF levels, and the presence of depression in lymphoma patients receiving R-CHOP chemotherapy." (PMID 39355088, 2024). "It is possible that EEG alpha power reflects changes in excitatory and inhibitory pathways in depression through the generalized effects of brain-derived neurotrophic factor (BDNF) on cortical excitability processes." (PMID 39338848, 2024). "For example, for many years, it was accepted that BDNF or activation of the TrkB receptor reduced anxiety and depression." (PMID 38228888, 2024). "Experimentally, oral administration of live L. murinus and L. animalis to LPS‐challenged mice yielded similar effects to ST in ameliorating depression, elevating 5‐HT and BDNF, and reducing proinflammatory cytokines." (PMID 39619956, 2024). "The cAMP/CREB/BDNF is a crucial signaling pathway in regulating hippocampal neuronal regeneration in depression." (PMID 38389919, 2024). "The neurobiological mechanisms underlying depressive and anxiety disorders have been shown to involve an altered BDNF signaling pathway in subjects with depression." (PMID 38255209, 2024). "Ononin treatment significantly decreased depression-like behaviors and activated BDNF/TrkB/CREB signaling pathways in the frontal cortex and hippocampus of chronic mild stress -induced depressive rats." (PMID 38337722, 2024). "Pairwise meta-analyses demonstrated that all exercise modalities significantly increased BDNF levels in patients with depression, with AERE, RE, and yoga showing particularly pronounced effects." (PMID 40226670, 2024). "For instance, in the hippocampus, BDNF is vital for neurogenesis and synaptic plasticity, influencing mood regulation and the pathophysiology of depression." (PMID 39126038, 2024). "Although no genes have been robustly associated with the aetiology of both migraine and depression, genes from serotonergic, dopaminergic, and GABAergic systems together with variants in the MTHFR and BDNF genes remain strong candidates." (PMID 38525706, 2024). "Considering these discoveries, studies have focused on the potential of using BDNF as a specific indicator of the depression state and recovery." (PMID 38542252, 2024). "Postmortem studies have demonstrated a decreased expression of BDNF and TrkB in the prefrontal cortex and hippocampus of suicide subjects with major depression." (PMID 39042346, 2024). "Further, plasma BDNF levels in patients with depression are significantly lower than those in individuals with normal BDNF levels, and this situation is more severe in older individuals." (PMID 39648800, 2024). "In support, there is a significant inverse relationship between BDNF blood levels and depression scores in depressed patients." (PMID 38315652, 2024). "Several lines of evidence involve BDNF in depression, as its expression is lower in depressed patients." (PMID 38928361, 2024). "Nevertheless, the keywords with the highest citation bursts in recent years have been “NMDA receptor blockade”, “Antidepressant”, “Oxidative stress”, “Treatment resistant depression”, “Ketamine”, “Pathophysiology”, and “BDNF”." (PMID 38974036, 2024). "The relationship between miR-206 and BDNF has been investigated in some diseases like schizophrenia (SZ), depression, and alcoholism." (PMID 38334898, 2024).
depression (continued). "Even more clinically relevant, there is evidence regarding the potential to integrate blood BDNF levels with Hamilton Depression Rating Scale scores to predict treatment response during the early phases of therapy, prior to observable symptom changes." (PMID 39227372, 2024). "Neuronal activation in the IL by using a chemogenetic tool reversed the depression- and anxiety-like phenotypes induced by estradiol withdrawal and induced accordingly the upregulation of BDNF/β-catenin in the IL and BLA." (PMID 38743109, 2024). "Studies, including those on compounds like Ginsenoside Rb1, have shown that the BDNF/TrkB pathway can reverse depression-like behaviors induced by CUMS." (PMID 41221079, 2024). "Chronic stress, a well-established risk factor for MDD, has been shown to decrease BDNF expression in critical brain regions such as the hippocampus and prefrontal cortex (PFC), contributing to the neuronal atrophy observed in depression." (PMID 39684808, 2024). "A large amount of data, in vivo and in vitro, support the role of BDNF in regulating of body weight, metabolic homeostasis, major depressive disorder, schizophrenia, and bipolar disorder." (PMID 40255947, 2024). "Accumulating evidence indicates that BDNF and β-catenin play a critical role in the pathophysiology of depression." (PMID 38743109, 2024). "NIBS effectively improves sleep quality, structure, depression levels, and BDNF levels in PSSD patients, while also being safe." (PMID 39539650, 2024). "Our previous research demonstrated that BDNF is essential for protecting sensorimotor function, and alleviating depression, anxiety‐like behaviors, and cognitive impairment after ICH." (PMID 39690816, 2024). "Depression and Alzheimer’s disease have comparable pathophysiological processes, such as impaired BDNF, compromised transforming-growth-factor-β1 (TGF-β1) signaling, and abnormal TNF-α signaling." (PMID 39459643, 2024). "A systematic review revealed that CSF levels of GABA, somatostatin and brain-derived neurotrophic factor (BDNF) are reduced in patients with depression." (PMID 38539252, 2024). "The over-expression of FXR in the hippocampus in naïve rats led to depression-like symptoms and reduced the expression of BDNF in the hippocampus." (PMID 39200564, 2024). "The elucidated mechanism of ZZCD through Six3os1/KMT2A/H3K4me3 pathway and the subsequent stimulation of BDNF expression can lead to targeted and effective treatments for depression, which can be further investigated and developed." (PMID 38818577, 2024). "Diets high in refined carbohydrates and saturated fat have additionally been shown to reduce brain-derived neurotrophic factor (BDNF) in the hippocampus, resulting in impaired spatial memory and increased risk of depression." (PMID 39866690, 2024). "Previous studies have shown that rTMS treatment increases the expression of BDNF and that decreased BDNF levels in depression are normalized after rTMS treatment." (PMID 37755583, 2024). "In animal models of depression, naringenin treatment has been shown to upregulate BDNF, SHH, GLI1, NK2 Homeobox 2 (NKX2.2), and Paired box protein Pax-6 (PAX6)." (PMID 39478958, 2024). "Encouragingly, specific strains of probiotics, such as Bifidobacterium, have demonstrated the capacity to mitigate depression by increasing BDNF levels and reducing oxidative stress." (PMID 38919504, 2024). "Recent research has indicated that depression is a consequence of reduced BDNF expression in the brain and increasing BDNF expression through antidepressant therapy thus shows positive response in the treatment of depression." (PMID 38818577, 2024). "Preclinical evidence has shown that idecreased BDNF levels in the hippocampus and prefrontal cortex (PFC) is associated with bilateral ovariectomy, leading to effective depression due to estrogen deficiency in mice." (PMID 38255289, 2024).